ITGAX (integrin subunit alpha X)
Diseases named in the same sentence as ITGAX in open-access papers (continued):
Sharing a sentence is not in itself a finding about the gene and the disease.
cancer (117 papers, 2003 to 2026). A tumor composed of atypical neoplastic, often pleomorphic cells that invade other tissues. "ITGAX has previously been implicated in multiple cancers and inflammatory diseases." (PMID 39845786, 2024). "Among the four cancer cell lines, ITGAX exhibited the highest expression level in SH-10-TC cells and the lowest in LMSU cells." (PMID 39845786, 2024). "The ITGAX subunits are one of the most widely overexpressed proteins in various cancers, rendering them potential targets for antitumor therapies." (PMID 39015503, 2024). "At the individual gene level, ITGA8 and ITGA9 were down-regulated in 11 out of the 15 cancers, whereas ITGAX, ITGB4, and ITGA6 were more frequently up-regulated in tumors relative to adjacent normal tissues (right)." (PMID 39436262, 2024). "ITGAX, a component of integrin family, was proven to promote angiogenesis in cancer development and aggressiveness." (PMID 33403050, 2021). "MUC1 and ITGAX were highly expressed in primary STS compared to some other types of cancer and they had a significant co-expression pattern in STS." (PMID 31739284, 2019). "In contrast, ITGAX is the most widely overexpressed subunit among the profiled cancers (1.54 to 8.11 linear fold change)." (PMID 30046394, 2018). "Three (ITGAX, STK39 and C6) are found to be associated with aggressive cancer in GWAS and QTL studies." (PMID 29738578, 2018). "Additionally, ITGAX was found to regulate the expression of programmed cell death protein ligand‐1 (PD‐L1), which was a critical component of the cancer immune evasion machinery, being a promising immunotherapy target clinically effective." (PMID 40778650, 2025). "ITGAX may play a critical role in cancer progression by modulating the EMT pathway." (PMID 39845786, 2024). "Expression of ITGAX was altered in BRCA and correlated with cancer progression and poor survival, which was a novel focus of therapeutic intervention in BRCA." (PMID 40778650, 2025). "Of note, consistent with the co-amplification profile of ITGAD, ITGAL, ITGAX, and ITGAM, we observed similar dysregulation patterns for them in cancers (belonging to one sub-cluster), validating our analytic pipeline." (PMID 39436262, 2024). "For the myeloid-derived cancer cell lines, we identified specific surface markers (e.g., ITGAM, ITGAX, CD68, CD86) usually present on monocytes, neutrophils, and macrophages, positively contributing to the BAY-155, EPZ-5676, and Brequinar group." (PMID 31253180, 2019). "However, the biological mechanisms of the interactions between TNXB-SDC4, THY1-(ITGAX+ITGB2), ICAM1-(ITGAX+ITGB2), and C3-(ITGAX+ITGB2) ligand-receptor pairs in cancer remain unclear and warrant further investigation." (PMID 37954130, 2023). "In addition, ITGAL, ITGAX, and TMEM119 were also strongly correlated with macrophages and other immune cell populations in LUAD and LUSC as well as across a panel of human cancer types." (PMID 37835514, 2023).
neurodegenerative disease (18 papers, 2015 to 2025). A disorder of the central nervous system characterized by gradual and progressive loss of neural tissue and neurologic function. "Significant enrichment of microglia and elevation of ITGAX are observed after IS, which indicates a unique microglial cell characteristic related to neurodegenerative diseases that emerged after IS." (PMID 40933575, 2025).
ITGAX also shares sentences with these, for which no sentence is quoted: colitis (115 papers); Insulin resistance (62); viral infection (59); Sepsis (30); malaria (28); asthma (26); breast cancer (26); influenza (25); liver fibrosis (22); lung carcinoma (19); Arthritis (17); rheumatoid arthritis (17); Splenomegaly (16); Stroke (16); parasitemia (15); inflammation (14); Allergy (13); bacterial infection (13); colorectal cancer (13); multiple sclerosis (13); pancreatic cancer (13); allergic asthma (11); pulmonary fibrosis (11); eosinophilia (10); sarcoidosis (10); HIV-1 infection (9); infectious disease (9); experimental autoimmune encephalomyelitis (8); inflammatory bowel disease (8); Sjögren’s syndrome (8).
A further 360 diseases each share a sentence with ITGAX in 7 papers or fewer.